ERBB2 (erb-b2 receptor tyrosine kinase 2)
Diseases named in the same sentence as ERBB2 in open-access papers (continued):
Sharing a sentence is not in itself a finding about the gene and the disease.
breast cancer (continued). "For an erbB2 model, we used a truncated form of Neu that models a form of erbB2 lacking the extracellular domain present in approximately 30% of HER2-positive breast cancer patients, for whom it is associated with a worse prognosis." (PMID 25200860, 2014). "Interestingly, a recent report has identified a requirement for PKCδ in erbB2-driven proliferation of breast cancer cells, and erbB2 drives aberrant Ras pathway signaling." (PMID 24528676, 2014). "These are, however, totally missing from breast cancers harboring ErbB2 amplification." (PMID 24709902, 2014). "Moreover, ILK expression has an impact on ErbB2-driven mammary tumor onset, and disruption of ILK inhibits proliferation and invasion and sensitizes ErbB2 tumor cells to apoptotic cell death." (PMID 25606594, 2014). "Validated cancer drivers such as ERRBB2, EGFR, and KRAS demonstrated high copy number versus mRNA expression correlation in the corresponding cancer types they regulate (ERBB2 r = 0.9 in breast cancer, EGFR r = 0.8 in lung adenocarcinoma, KRAS r = 0.9 in ovarian cancer)." (PMID 24874471, 2014). "In addition to being a reliable biomarker of aggressive and invasive disease, ErbB2 is also a validated therapeutic target in breast cancer." (PMID 24709902, 2014). "The use of Imatinib, for chronic myeloid leukemia and other solid tumors, of Trastuzumab and Lapatinib, for ERBB2 positive breast cancer, and of Vemurafenib, for BRAF mutant melanomas, are emblematic examples of how genomic alterations can be used to target cancer cells." (PMID 25193853, 2014). "Previous data suggested that CHIP could induce ErbB2 ubiquitination and degradation in breast cancer cells." (PMID 24722501, 2014). "ErbB3 may be considered as a valuable biomarker to predict the efficacy of EGFR- and/or erbB2-targeted therapy in the treatment of NSCLC and erbB2+ breast cancer, respectively." (PMID 24886126, 2014). "Thanks to the simultaneous availability of IHC ER, PR and ERBB2 status for 2259 breast cancer samples of our pooled series, including 294 CL samples, we could redefine the TN status at the protein level as did Prat and colleagues." (PMID 25277734, 2014). "We used longitudinal proteomic data of ErbB receptors and downstream targets in the ErbB-2 amplified breast cancer cell lines BT474, SKBR3 and HCC1954 treated with erlotinib, trastuzumab or pertuzumab, alone or combined, up to 60 minutes and 30 hours, respectively." (PMID 24970389, 2014). "We found that patients harboring tumors of the luminal-like subtype have a better prognosis than those with basal-like breast cancer, a similar prognosis to those with ERBB2+, luminal B or claudin-low tumors, but a worse prognosis than patients with luminal A or normal-like breast tumors." (PMID 25076125, 2014). "Moreover, expression of p85ErbB2 under the control of a heterologous promoter can render cells resistant to lapatinib and other ErbB2 targeted drugs in otherwise sensitive ErbB2+ breast cancer cells." (PMID 24551203, 2014). "In addition to its pathological role in breast cancer, Erbb2 is essential for normal embryonic development." (PMID 25269082, 2014). "In addition to LRP1, eHsp90 activates EGFR signaling in breast cancer, as shown by its interaction with the extracellular domain of HER2/Neu/ErbB2, the ligandless co-receptor for EGFR family members." (PMID 24805867, 2014). "Although some pathological factors, including estrogen receptor (ER), progesterone receptor (PR) and c-erbB-2 (HER2), have been widely used as a reference in clinical diagnosis and treatment, their prognostic value for breast cancer still has certain limitations." (PMID 25116444, 2014). "Although the direct connection between ErbB2 and Wnt may be missing, elevated levels of the oncogenic Met receptor tyrosine kinase, which is often upregulated in ErbB2 positive breast cancers with poor prognosis, induces Wnt and EMT signatures." (PMID 24709902, 2014).
breast cancer (continued). "However, as ErbB2/HER2-positive breast cancers represent approximately 25% of all breast cancer cases, there is a need to identify additional kinases that can acquire driver characteristics in breast cancer progression and impact on therapy response." (PMID 24467886, 2014). "And the other researchers also suggested that expression of ERBB-2 is much lower on MB tumor cells than on breast cancer cells, so they are not susceptible to ERBB-2 monoclonal antibodies, like trastuzumab (Herceptin)." (PMID 24986561, 2014). "Importantly, we show that PUVA can trigger significant apoptosis in ErbB2+ breast cancer models of acquired therapeutic resistance to lapatinib and similar ErbB2 targeted therapies." (PMID 24551203, 2014). "The same could be shown for the human erbB2-positive breast cancer cell line SK-BR3 as well as for the erbB2-negative and hormone receptor-positive cell line MCF-7." (PMID 23963762, 2014). "Interestingly, ErbB2 activation by constitutive active Raf-1 in breast cancer cells is implicated in MET, the antagonistic process of EMT, further complicating the role of the ErbB2 in this process." (PMID 24709902, 2014). "In identifying the key downstream mediators through which erbB3 contributes to chemoresistance, we found that elevated expression of erbB3 conferred paclitaxel resistance in erbB2+ breast cancer cells via PI-3 K/Akt-dependent upregulation of Survivin, a critical inhibitor of apoptosis." (PMID 24886126, 2014). "Our findings suggest that PHLDA1 might have key inhibitory functions in ErbB2 driven lung and breast cancer cells and a better understanding of its functions might point at novel therapeutic options." (PMID 25238247, 2014). "In addition to ErbB2, several studies using mammary gland directed overexpression of polyoma middle-T antigen (PymT) to model metastatic breast cancer has been carried out." (PMID 24709902, 2014). "Examples of cancer biomarkers routinely used in the clinic include α-fetoprotein (AFP) for diagnostics and management of testicular cancer, MUC16 (cancer antigen 125 or CA-125) for ovarian cancer, ERBB2 (HER2) protein for breast cancer, and prostate specific antigen for prostate cancer." (PMID 25521819, 2014). "We have published a series of articles indicating that estrogenic promotion of erbB2 kinase activity in mammary tumor cells requires erbB3, and the activation of erbB3 signaling plays an essential role in erbB2-mediated therapeutic resistance to tamoxifen, trastuzumab, and paclitaxel." (PMID 24886126, 2014). "The role of p130Cas/BCAR1 as a mediator of ErbB2 signalling was initially demonstrated in breast cancer cell lines devoid of ErbB receptors, in which over-expression of ErbB2 was sufficient to induce cell migration by triggering the coupling between p130Cas/BCAR1 and Crk." (PMID 25606587, 2014). "Trastuzumab is most beneficial for patients with ErbB2 positive, early stage breast cancer." (PMID 24709902, 2014). "We speculate that PHLDA1 might have key inhibitory functions in EGFR and ErbB2-driven lung and breast cancer cells and a better understanding of its functions might point at novel therapeutic options through modulation of this important negative feedback loop." (PMID 25238247, 2014). "Human breast cancer is a fairly heterogeneous disease, which differs among others in expression levels for hormone (e.g., estrogen and progesterone) and growth factor (e.g., ErbB2) receptors." (PMID 24795638, 2014). "In addition, it has been reported that divalent or multivalent forms of the EC1 peptide fused-Fc-liposome selectively target ErbB2-overexpressing breast cancer cells and are efficiently internalized into cells." (PMID 25190023, 2014). "Similarly, elevated expression of activated forms of Neu/ErbB-2 and ErbB3 are involved in the induction of mammary tumors in MMTV-Neu transgenic mice." (PMID 25516216, 2014).
breast cancer (continued). "Moreover, MMTV-NDL mammary tumour cells, which lack Cre recombinase but express the same ErbB2/Neu oncogene used in the MMTV-NIC model, are tolerated in an FVB/N background (unpublished observations; Muller WJ)." (PMID 24457046, 2014). "SISH was used to determine ErbB2 status in human breast cancer samples." (PMID 25238247, 2014). "In one such study, an engineered pseudotyped VSV encoding a single-chain antibody against the Her2/neu receptor (ErbB2) was found to yield low titer in target mammary cancer cells expressing ErbB2, and directed evolution was then used to improve viral fitness in these cells." (PMID 25010337, 2014). "Thus, in addition to its effects on DNA and the formation of ICL, PUVA represents a novel ErbB2 targeted therapy for the treatment of ErbB2+ breast cancers, including those that have developed resistance to other ErbB2 targeted therapies." (PMID 24551203, 2014). "Interestingly, shRNA-based depletion of PTEN that is inactivated in 40% of ErbB2 positive breast cancers, results in further enrichment of CSC population and generation of larger mammary tumors with extensive metastasis to lymph nodes, liver, and lung." (PMID 24709902, 2014). "To investigate the wider applicability of our multi-parametric image analysis platform, we used it to classify 44 known human breast cancer cell lines that have been categorized as basal-A, basal-B, luminal or luminal/ERBB2+ based on their gene expression profiles." (PMID 25289886, 2014). "ErbB2 is expressed at high levels on the plasma membrane of SK-BR-3 breast cancer cells." (PMID 25260758, 2014). "Few antibody therapeutics other than those against ErbB receptors have proven effective in breast cancer and this might be a matter not only of the importance of ErbB2 in HER2amp cells, but also the down-regulation of other signaling pathways in these cells." (PMID 24655548, 2014). "In this review we will mainly discuss ErbB2-induced invasion in the context of breast cancer, as ErbB2 function is most extensively studied in breast cancer, where its aberrant overexpression and activation is strongly linked to an invasive, aggressive phenotype and poor prognosis." (PMID 24709902, 2014). "In mouse mammary tumor virus (MMTV)/ErbB2 mice, conditioned deletion of β1 in mammary epithelial cells resulted in a significant 33-day delay in the induction of mammary tumors and an increase in the number of apoptotic cells, indicating the importance of β1 in mammary tumorigenesis." (PMID 25606594, 2014). "In this study, we investigated whether HRG-β1/ErbB3 induces the process of EMT with involvement of Smad2 activation in the ErbB2-overexpressing SK-BR-3 cell line and luminal A breast cancer cell line MCF7." (PMID 23937725, 2013). "To gain new insights into the functional relationship linking MBP-1 and ERBB2 in breast cancer, we have investigated the effects of MBP-1 expression on endogenous ERBB2 transcript and protein levels, as well as on transcription promoter activity, by transient-transfection of SKBr3 cells." (PMID 23421821, 2013). "Moreover, treatment of ErbB2-driven mouse mammary tumors with ErbB2 neutralizing antibodies together with v-akt murine thymoma viral oncogene homolog 1 (AKT) inhibitors results in increased CTL infiltration and delayed tumor outgrowth." (PMID 23408142, 2013). "The c-Src kinase is overexpressed or hyperactive in a range of human tumors, including breast cancer where as many as 70% cases have been reported with c-Src overexpression along with EGFR/ErbB1 or ErbB2, leading to conjectures of possible synergy between Src and the ErbBs in breast cancer." (PMID 23637902, 2013). "However, about two third of the ERBB2 overexpressing breast cancer patients are found to be Trastuzumab resistant ab." (PMID 23829771, 2013). "Luminal breast cancers are more often ER and/or PR positive or have over expression of ERBB2." (PMID 23401782, 2013).
breast cancer (continued). "Moreover, ErbB2-driven mammary tumors display reduced surface MHC class I levels in transgenic mice." (PMID 23408142, 2013). "Moreover, we showed that LOXL2 expression correlates with metastasis and poor survival in ErbB2-positive breast cancer patients." (PMID 23971878, 2013). "LOXL2 may also be a beneficial marker for breast cancer patients that could benefit most from anti-ErbB2 therapy." (PMID 23971878, 2013). "Concordantly, several authors reported that despite the fact that IHC is currently used for human breast cancer erbB-2 protein categorisation, the application of different, common, commercially available erbB-2 antibodies produces variability in the IHC results." (PMID 24386251, 2013). "Finally, we showed that high LOXL2 expression correlates with poor prognosis in ErbB2-positive breast cancer patients, demonstrating a strong link between LOXL2 and ErbB2 and aggressive cell behavior." (PMID 23971878, 2013). "Our data also suggest that the ERBB2+ subset of human breast cancer may arise from breast cells that are low in Wnt signaling." (PMID 24265712, 2013). "Finally, we found LOXL2 expression to be correlated with decreased overall survival and metastasis-free survival in breast cancer patients with ErbB2-positive tumors." (PMID 23971878, 2013). "Thus, our data provide a strong basis to explore the therapeutic potential of MM-121 in combination with trastuzumab in erbB2+ breast cancer patients resistant to trastuzumab." (PMID 24215614, 2013). "It is unclear whether an erbB3-targeted therapy may abrogate erbB2-mediated paclitaxel resistance in breast cancer." (PMID 24168763, 2013). "Indeed, ERBB2+ breast cancer cells with increased expression of PGC-1α display elevated expression of glutamine metabolism genes." (PMID 24304688, 2013). "The activated form of ERBB3 was detected in human breast cancers with amplified ERBB2 expression." (PMID 23593223, 2013). "Clinically, TNBCs are defined by their lack of expression of the oestrogen receptor α (ERα), progesterone receptor (PR) and HER2 (ERBB2), are generally of high histological grade, poorly differentiated and more aggressive compared to other subtypes of breast cancer." (PMID 23436775, 2013). "We found a positive correlation between the levels of the two receptors, suggesting the existence of mechanisms of co-regulation and possibly functional cooperation, especially in breast cancers where ERBB2/HER2 increased levels cannot alone sustain/explain the malignant behavior." (PMID 24165569, 2013). "The most notable overall observation in this investigation is the lack of evidence to support a significant association between ERBB2 genomic sequence variants (SVs) and HBC initiation, despite the wealth of information supporting its role in breast cancer progression." (PMID 24386251, 2013). "Thus, our studies demonstrate that MM-121 overcomes paclitaxel resistance and enhances paclitaxel-induced apoptosis in the studied erbB2-overexpressing breast cancer cell lines via specific downregulation of Survivin." (PMID 24168763, 2013). "However, erbB3 has been shown to serve as a critical co-receptor of erbB2, and its expression is a rate-limiting factor for erbB2-mediated breast cancer cell survival and proliferation." (PMID 24168763, 2013). "Strikingly, neratinib showed promising activity in ERBB2-overexpressing breast cancers and could potentially be approved as a first-line therapy in locally advanced or metastatic ERBB2-overexpressing breast cancers." (PMID 23630663, 2013). "Using this multi-level model we studied the ErbB2-driven vaccination effect in breast cancer." (PMID 23734974, 2013). "Perturbing ErbB2 activity with an anti-ErbB2 antibody has been used for breast cancer therapy." (PMID 23308187, 2013).
breast cancer (continued). "Furthermore, the prognostic significance of PIK3R1 underexpression persisted in the overall series (p = 0.0013) and in breast cancer subgroups characterized by ERα + (p = 0.0076), PR + (p = 0.043), ERBB2+ (p = 0.018) and also ERBB2- (p = 0.024)." (PMID 24229379, 2013). "Furthermore, ERBB2+ breast cancer cells with reduced expression of PGC-1α or when treated with C29, a pharmacological inhibitor of ERRα, exhibit diminished expression of glutamine metabolism genes." (PMID 24304688, 2013). "Most metastatic breast cancers show expression for either EGFR or erbB2, and less often for both." (PMID 24168763, 2013). "Our data suggest that further studies regarding the suitability of MM-121 for treatment of breast cancer patients whose tumors overexpress erbB2 and become resistant to trastuzumab may be warranted." (PMID 24215614, 2013). "Given our results from analysis of human TMAs that indicate 31% of HER2 positive breast cancers lack LKB1 expression, we investigated whether the loss of LKB1 expression would alter the latency of ErbB2-mediated tumorigenesis." (PMID 23451056, 2013). "HER2/ERBB2 overexpression is detected in canine mammary tumors to varying extends (18–74%)." (PMID 24098698, 2013). "Thus, identification of novel therapeutic strategies/agents to overcome trastuzumab resistance is vital to improve the survival of breast cancer patients whose tumors overexpress erbB2." (PMID 24215614, 2013). "We and others have also observed an elevated expression of the endogenous mouse erbB3 in the mammary tumors derived from erbB2/neu-transgenic mice; and the increased erbB3 forms physical and functional interactions with the transgene-encoded erbB2 to promote mammary tumorigenesis." (PMID 24168763, 2013). "Albeit miR-125b has been demonstrated to be tumor suppressor in breast cancer by down-regulating ERBB2 and ERBB3, several studies have showed its property to increase resistance of cancer cells, including breast cancer cells, to anticancer drug, resulting in subsequent recurrence and metastasis." (PMID 23321005, 2013). "In the current study, wedemonstrated enhanced immune cell recruitment and reduced T cell co-inhibitory pathwaysin tumors that lack mammary epithelial expression of the pro-inflammatory enzyme COX-2,coincident with delayed ErbB2 oncogene-driven mammary tumor development." (PMID 24004819, 2013). "As MP-RM-1 inhibits both ligand-dependent and -independent activation of erbB3, we speculate that hMP-RM-1 might exert more potent antitumor activity than MM-121 against erbB2-overexpressing breast cancer." (PMID 24168763, 2013). "ERBB2/Neu-induced breast cancer cells with increased expression of PGC-1α (α-1.1) displayed two-fold enrichment or greater for PGC-1α and ERRα at the promoter of glutamine metabolism genes, supporting the tight association between the ERRs and PGC-1 s in the control of metabolic genes." (PMID 24304688, 2013). "In addition, activation of the erbB2/erbB3/PI-3K/Akt signaling also results in resistance to hormonal therapy and chemotherapy in breast cancer treatment." (PMID 24215614, 2013). "Finally, we demonstrate that the PGC-1α-mediated control of glutamine metabolism has clinical relevance in ERBB2+ breast cancer patients." (PMID 24304688, 2013). "Furthermore, in the ErbB2 transgenic mouse model of breast cancer, Her2 is constitutively activated in the mammary epithelium, resulting in expansion of mammary CSCs through decreased asymmetric and increased symmetric self-renewing divisions." (PMID 24238140, 2013). "AR expression in breast cancers is independent of estrogen receptor alpha (ERα) status and is frequently associated with overexpression of the ERBB2 oncogene." (PMID 23593223, 2013).